HSPB7 (heat shock protein family B (small) member 7)
Diseases named in the same sentence as HSPB7 in open-access papers (continued):
Sharing a sentence is not in itself a finding about the gene and the disease.
thyroid cancer (1 paper, 2018). "Furthermore, HSPB7 relative promoter methylation was significantly increased in nine cancer types by 1.07‐ to 1.37‐fold and reduced only in lung squamous cell and thyroid cancers by 0.9‐ and 0.83‐fold, respectively (P < 0.005)." (PMID 29577611, 2018).
viral infection (1 paper, 2024). "Additionally, HSPB7 (small heat shock protein family B member 7) is known to respond to stressors such as hypoxia and viral infection." (PMID 38675838, 2024).
tumor (12 papers, 2014 to 2025). "Of note, genome‐ and epigenome‐wide associations of SRARP and HSPB7 with survival strongly support their tumor suppressor functions." (PMID 29577611, 2018). "Furthermore, genome‐ and epigenome‐wide associations of SRARP and HSPB7 with survival also strongly support their function as tumor suppressors." (PMID 29577611, 2018). "Of note, tumor suppressor functions of SRARP and HSPB7 are associated with the downregulation of Akt and ERK signaling in cancer cells." (PMID 29577611, 2018). "Subsequently, the associations between the promoter methylation and expression values for SRARP and HSPB7 in eighteen tumor datasets were measured by PCC and linear regression curve estimation." (PMID 29577611, 2018). "This study suggests that SRARP and HSPB7 are gene pairs on 1p36.13 that have tumor suppressor functions and are highly regulated by gene‐level deletions and epigenetic silencing across malignancies of multiple tissue origins." (PMID 29577611, 2018). "These signaling effects of SRARP and HSPB7 correspond with their potent tumor suppressor functions in these two lines." (PMID 29577611, 2018). "This study reveals that SRARP and its gene pair, HSPB7, are epigenetically regulated tumor suppressors and predict clinical outcome in malignancies." (PMID 29577611, 2018). "The results of the current study strongly suggest that SRARP and HSPB7 are tumor suppressor genes located 5.2 kb apart on 1p36.13." (PMID 29577611, 2018). "In view of the fact that SRARP and HSPB7 are co‐expressed gene pairs with tumor suppressor functions, the possibility of similarities between the molecular features of these proteins was further investigated." (PMID 29577611, 2018). "Through the genome-wide expression analysis in RCCs, we identified HSPB7 as a candidate tumor suppressor gene because of its common and significant downregulation in RCCs." (PMID 24585183, 2014). "Emerging evidence suggests HSPB7 plays a significant role in tumour development." (PMID 40461943, 2025). "HSPB7, a member of the heat-shock protein family, has been shown to function mainly in cardiac disease regulation; however, studies regarding its ability to regulate tumor progression are very limited." (PMID 33381581, 2020). "The combination of epigenetic silencing and gene‐level deletions of SRARP and HSPB7 across multiple malignancies raised the question whether these genes have a tumor suppressor function." (PMID 29577611, 2018). "In addition, gene expression and promoter methylation of HSPB7 showed a significant inverse correlation in seven tumor types (P < 0.05)." (PMID 29577611, 2018). "In addition, survival analysis was carried out in ICGC cohorts using SRARP and HSPB7 copy numbers calculated as log2 (tumor/normal) values." (PMID 29577611, 2018). "Therefore, SRARP or HSPB7 overexpression in cancer cell lines leads to a marked reduction in clonogenicity, suggesting that these proteins function as tumor suppressors." (PMID 29577611, 2018). "Therefore, SRARP and HSPB7 gene expression and promoter methylation were analyzed in eighteen tumor types and their respective normal tissues using TCGA datasets as explained in methods." (PMID 29577611, 2018). "In summary, SRARP and HSPB7 are tumor suppressors that are commonly inactivated in malignancies." (PMID 29577611, 2018). "Importantly, SRARP and HSPB7 have tumor suppressor functions in clonogenicity and cell viability associated with the downregulation of Akt and ERK." (PMID 29577611, 2018). "We also performed colony formation assay in 3 other RCC cell lines (Caki-2, A498 and 786-O) using the same vectors, and confirmed similar growth-suppressive effects, implying that HSPB7 may function as a tumor suppressor gene." (PMID 24585183, 2014).
tumor (continued). "However, further studies are needed to clarify the detailed tumor suppressor function of HSPB7 in RCC." (PMID 24585183, 2014). "Ectopic expression of HSPB7 significantly impaired colony-forming ability for 5 RCC cell lines, indicating that HSPB7 may function as a tumor suppressor gene." (PMID 24585183, 2014). "Therefore, the signaling pathways that are regulated in SRARP‐ and HSPB7‐mediated tumor suppression may vary based on the tissue origin of tumors." (PMID 29577611, 2018). "Therefore, an interaction with 14‐3‐3 creates another common molecular feature between HSPB7 and SRARP proteins, which may present an underlying mechanism for their function as tumor suppressors." (PMID 29577611, 2018). "We classified UM tumor cells into six distinct subclusters based on marker gene expression: C0 WSB1+ TCs, C1 EEF1A1+ TCs, C2 HSPB7+ TCs, C3 XIST+ TCs, C4 GNG11+ TCs, and C5 PCOLCE+ TCs." (PMID 39635521, 2024). "Conversely, only four of the thirteen deletions that resulted in a significant decrease in expression in tumors were previously identified as down-regulated when comparing normal and tumor tissue (CRYAB, SACS, HSPB7, and HSPB2)." (PMID 38816397, 2024). "Next, promoter methylation ratios of tumor to normal for SRARP and HSPB7 genes were calculated in each tumor type and statistical significance was tested for the differences between tumor and normal samples in each dataset using a t‐test." (PMID 29577611, 2018). "Tumor suppressor functions of SRARP and HSPB7 are supported by the fact that the overexpression of these genes markedly suppresses colony formation and cell viability in cancer cell lines." (PMID 29577611, 2018). "In agreement with our results, HSPB6 and HSPB7 have been found downregulated in several tumour types, and we report here this downregulation in all subtypes of BRCA is possibly supporting a role as tumour suppressor genes." (PMID 29954368, 2018). "Median SRARP and HSPB7 expression levels were obtained for tumor and normal samples in each dataset and differential gene expression values were calculated as follows: log2 (RPKM+1)‐transformed median values of tumor ‐ log2 (RPKM+1) of normal." (PMID 29577611, 2018). "In view of the integrated nature of Akt and ERK signaling, the downregulation of both these pathways may explain the potent tumor suppressor effects of SRARP and HSPB7 on these cancer cells." (PMID 29577611, 2018).
cancer (5 papers, 2014 to 2024). A tumor composed of atypical neoplastic, often pleomorphic cells that invade other tissues. "Introduction of HSPB7 into these two cancer cell lines caused significant decrease in the number of colonies, compared with corresponding mock-transfected controls." (PMID 24585183, 2014). "Finally, the association of SRARP and HSPB7 copy numbers with survival was examined using ICGC datasets in a total of 1177 patients with cancer." (PMID 29577611, 2018). "Moreover, ICGC datasets were analyzed to further assess the association of SRARP and HSPB7 gene expression with survival in patients with cancer using donor centric data with more than 27 years of follow up." (PMID 29577611, 2018). "As expected, SRARP and HSPB7 copy numbers showed an identical predictive pattern for survival in patients with cancer." (PMID 29577611, 2018). "In this respect, TCGA Pan‐Cancer datasets were analyzed as explained in methods to examine the association of SRARP and HSPB7 methylation, expression, and mutations with survival across malignancies of multiple tissue origins." (PMID 29577611, 2018). "Collectively, these findings strongly suggest epigenetic silencing as a key factor in the regulation of SRARP and HSPB7 expression across tumors and cancer cell lines of multiple tissue origins." (PMID 29577611, 2018). "Subsequent functional analysis revealed that HSPB7 was downregulated in cancer cells by hypermethylation." (PMID 24585183, 2014). "Consistently, restoration of HSPB7 expression was observed by the treatment of cancer cells with 5-Aza-dC." (PMID 24585183, 2014). "The second key finding in this study is that HSPB7 showed growth suppressive effect in cancer cells." (PMID 24585183, 2014). "Moreover, HSPB7 shows DNA hypermethylation in most tumors and all tested cell lines, and has histone deacetylation in most cancer cells." (PMID 29577611, 2018). "Importantly, analysis of TCGA Pan‐Cancer dataset demonstrated that SRARP and HSPB7 have an average loss of −0.15 copies across a total of 12 821 malignant samples (P < 0.001)." (PMID 29577611, 2018). "Next, the association of SRARP and HSPB7 methylation and expression with survival was examined in normal solid tissues derived from TCGA Pan‐Cancer datasets, which mostly constituted of histologically normal tissues adjacent to tumors." (PMID 29577611, 2018). "Finally, the effect of epigenetic silencing by DNA methylation and/or histone deacetylation strongly predicts SRARP and HSPB7 expression across multiple cancer cell lines." (PMID 29577611, 2018). "In addition, HSPB7 expression was significantly increased following 5‐aza‐dC treatment in all fourteen cancer cell lines by 5.9‐ to 923‐fold (P < 0.01)." (PMID 29577611, 2018). "Furthermore, HSPB7 expression was significantly increased following HDAC inhibition in thirteen cancer cell lines by 2.7‐ to 173‐fold (P < 0.01)." (PMID 29577611, 2018). "SRARP and HSPB7 genes were next investigated in predicting cancer outcome." (PMID 29577611, 2018). "Moreover, statistical modeling using regression analysis was performed to predict SRARP and HSPB7 expression based on their epigenetic regulation data by DNA demethylation and histone deacetylation reversal in fourteen cancer cell lines." (PMID 29577611, 2018). "Similarly, HSPB7 demonstrated low baseline expression levels in thirteen cancer cell lines with −ΔCT values measuring from −13.75 to −20.34." (PMID 29577611, 2018). "Therefore, the promoter methylation levels of SRARP and HSPB7 are significantly altered in multiple cancer types compared to their matched normal tissues, showing hypermethylation in the majority of changes." (PMID 29577611, 2018). "Ectopic introduction of HSPB7 in five RCC cell lines remarkably suppressed cancer cell growth." (PMID 24585183, 2014). "Consequently, ectopic introduction of HSPB7 suppressed RCC cancer cell lines growth." (PMID 39367275, 2024).
cancer (continued). "Therefore, SRARP or HSPB7 overexpression significantly reduces cell viability in cancer cell lines." (PMID 29577611, 2018). "Therefore, comparing SRARP and HSPB7 methylation between tumors and normal adjacent tissues may underestimate their actual hypermethylation levels in cancer." (PMID 29577611, 2018). "Our finding could contribute to better understanding of the novel function of HSPB7 in cancer." (PMID 24585183, 2014). "For example, in the HSP20 family, HSPB7 was positively enriched in 22 cancer types, while HSPB9 was negatively enriched in 25 cancer types." (PMID 33225964, 2020). "A total of fourteen cancer cell lines were treated with 5‐aza‐dC and TSA followed by the assessment of SRARP and HSPB7 expression using qRT‐PCR." (PMID 29577611, 2018). "However, HSPB7 expression is better predicted using its deacetylation levels in cell lines compared to methylation, indicating that histone deacetylation may be a key regulatory step for the inactivation of HSPB7 in cancer." (PMID 29577611, 2018). "Bisulfite sequencing of a genomic region of HSPB7 detected DNA hypermethylation of some segments of HSPB7 in RCC cells and concordantly 5-aza-2′-deoxycytidine (5-Aza-dC) treatment of cancer cells restored HSPB7 expression significantly." (PMID 24585183, 2014). "Subsequent quantitative PCR (qPCR) and immunohistochemical (IHC) analyses confirmed the downregulation of HSPB7 in RCC tissues and cancer cell lines in both transcriptional and protein levels." (PMID 24585183, 2014). "In addition, the fact that HSPB7 and SRARP genes were hypermethylated in fourteen and twelve cancer cell lines, respectively further supports the importance of DNA methylation in the epigenetic regulation of these genes." (PMID 29577611, 2018). "Expression of HSPB7 and SRARP in fourteen cancer cell lines." (PMID 29577611, 2018). "However, HSPB7 expression was not a robust predictor of cancer outcome in TCGA datasets and showed a mixed pattern." (PMID 29577611, 2018). "There was no significant change in HSPB7 differential expression in the remaining three cancers." (PMID 29577611, 2018). "However, HSPB7 gene expression did not significantly predict survival in ICGC cancer patients and normal tissues (P > 0.1)." (PMID 29577611, 2018).
myopathy (5 papers, 2016 to 2025). A disease of the muscle in which the muscle fibers do not function properly. "FLNC has been found to be the interaction protein of HSPB7, and the loss of HSPB7 in skeletal muscles can cause progressive myopathy with FLNC aggregation." (PMID 28827800, 2017). "We provided compelling evidence indicating that the loss of HSPB7 function is sufficient to induce the development of a progressive myopathy phenotype associated with myofibrillar disorganization and sarcolemma disruption in mice." (PMID 26929074, 2016). "Despite the less-severe phenotype, HspB7 CKO mutant mice showed a progressive myopathy phenotype with the aggregation and mislocalization of its interacting protein FLNC." (PMID 26929074, 2016). "We investigated the interaction of HspB7 and its α-crystallin domain with the wild-type (WT) C-terminal fragment of human filamin C (FLNC), containing immunoglobulin-like domains 22–24 and its three mutants associated with cardio- and myopathies." (PMID 40564978, 2025). "In mice, the complete lack of HSPB7 leads to a progressive myopathy associated with disarray of myofibrils." (PMID 32887649, 2020). "Interestingly, the amount of FLNC aggregation correlated with the severity of myopathy phenotype in HspB7 CKO muscle." (PMID 26929074, 2016). "Here, we found that skeletal-muscle-specific ablation of the HspB7 does not affect myogenesis during embryonic stages to postnatal day 1 (P1), but causes subsequent postnatal death owing to a respiration defect, with progressive myopathy phenotypes in the diaphragm." (PMID 26929074, 2016). "Collectively, our findings suggest that HSPB7 is essential for maintaining muscle integrity, which is achieved through its interaction with FLNC, in order to prevent the occurrence and progression of myopathy." (PMID 26929074, 2016).
cardiac disease (3 papers, 2017 to 2022). "In conclusion, our mouse model demonstrates that HSPB7 is required to maintain the structure and function of gap-junction complexes and intercalated discs, which has important implications for human heart disease." (PMID 28827800, 2017). "Thus, our mouse model demonstrates that HSPB7 is required for the structural integrity and function of gap-junction complexes and IDs, a finding which has vital implications for human heart disease." (PMID 28827800, 2017).
neurodegenerative disease (3 papers, 2018 to 2023). A disorder of the central nervous system characterized by gradual and progressive loss of neural tissue and neurologic function. "In addition, HSPB family, including HSPB7, act protectively on aggregation of several proteins containing an extended polyglutamine (polyQ) stretch, which are linked to a variety of neurodegenerative diseases." (PMID 29577611, 2018). "Although the mechanism in promoting osteogenesis is probably different from neurodegenerative diseases, the deletion of the N-terminus renders the protein less functional, abrogating osteogenic stimulation induced by full-length HSPB7." (PMID 37170285, 2023). "Moreover, the HSPB7 NTD mediates the HSPB7 anti-aggregating and pro-degradative activities against misfolded proteins involved in neurodegenerative diseases (NDs) via autophagy." (PMID 35281256, 2022).
infection (2 papers, 2014 to 2021). The state of being infected such as from the introduction of a foreign agent such as serum, vaccine, antigenic substance or organism.
cardiovascular disease (1 paper, 2022). "The data generated from both the human in silico and zebrafish in vivo assessments undertaken supports further investigation of the potential roles of API5, HSPB7, and LMO2 in human cardiovascular disease." (PMID 35548346, 2022).
HSPB7 also shares sentences with these, for which no sentence is quoted: idiopathic cardiomyopathies (2 papers); renal carcinoma (2); Atrophy (1); cataract (1); cervical cancer (1); clear cell renal cell carcinomas (1); co-infection (1); colorectal cancer (1); endotoxemia (1); gastric cancer (1); glioblastoma (1); hepatocellular carcinoma (1); Huntington disease (1); idiopathic dilated cardiomyopathy (1); Kennedy disease (1); lung adenocarcinoma (1); metastasis (1); neuropathy (1); non-small cell lung carcinoma (1); prostate carcinoma (1); Right ventricular cardiomyopathy (1); sarcopenia (1).